IDO1 (indoleamine 2,3-dioxygenase 1)
Diseases named in the same sentence as IDO1 in open-access papers (continued):
Sharing a sentence is not in itself a finding about the gene and the disease.
cancer (continued). "Indoleamine 2, 3-dioxygenase 1 (IDO1) is commonly expressed by cancers as a mechanism for evading the immune system." (PMID 36145311, 2022). "Recently, a novel role for IDO1 as an inflammatory modifier has been described, being the key factor of several pro-inflammatory pathways in cancer responsible for disease progression." (PMID 35408802, 2022). "Whereas IDO2 is expressed in a few cancers (four-to-six), both IDO1 and TDO2 show a much broader expression." (PMID 36286592, 2022). "In contrast, Tyk2ΔIEC tumors contained an increased number of Ido1-expressing cancer cells when compared to Tyk2fl/fl controls." (PMID 36185806, 2022). "In recent years, IDO1 inhibitors have been studied for cancer immunotherapy in clinical trials, usually in combination with other drugs, such as immune checkpoint inhibitors." (PMID 36185621, 2022). "IDO1 has been demonstrated to serve as a novel and reliable prognostic indicator for many types of cancer." (PMID 36139584, 2022). "IDO1 inhibition has shown to increase the therapeutic efficacy of checkpoint inhibitors, cancer vaccines, or even chemotherapy in mice and human tumors grafted into immunodeficient mice reconstituted with human lymphocytes." (PMID 36119020, 2022). "Both IDO1 and PD-L1 dampen antitumor immune responses in cancer, prompting immunotherapy development." (PMID 35058616, 2022). "IDO1 oxidizes tryptophan (TRP) to generate kynurenine (KYN), the substrate for 1-carbon and NAD metabolism and is implicated in pro-cancer pathophysiology and infection biology." (PMID 35245456, 2022). "IDO1 is activated in a variety of human cancers and demonstrates immunosuppression through the suppression of CD8+ Teffs and NKs, in addition to increased activity of Tregs and MDSCs." (PMID 35139879, 2022). "Of the 10 IDO1 expressing cancers, only 6 co-express TDO2, 3 co-express FAMID and 4 co-express each of the two Trp transporters, with ratios of 60%, 30%, 40% and 40% respectively." (PMID 36286592, 2022). "Emerging evidence shows that some of these genes, such as CHEMBL4685 (IDO1) and CHEMBL3286 (PLAU), are linked to cancer development." (PMID 35379165, 2022). "Functionally, IDO1 plays a key role in carcinogenesis and cancer immune escape by catalyzing the initial step of canine urinary ammonia pathway." (PMID 36304470, 2022). "Indoleamine 2,3-dioxygenase-1 (IDO1) is a rate-limiting tryptophan catabolic enzyme that is activated in many human cancers." (PMID 36034879, 2022). "IDO1 appears to be a promising therapeutic target as well as a prognostic predictor in different cancers." (PMID 36212460, 2022). "In this respect, the roles of arginase‐1 (ARG‐1) and indoleamine 2,3‐dioxygenase 1 (IDO1), involved in the catabolism of l‐arginine and l‐tryptophan, respectively, have been clearly established in the immunosuppressive network in cancer." (PMID 36054818, 2022). "Although IDO2 is expressed by cancer cells, when compared to IDO1, it contributes little to the accumulation of kynurenine pathway metabolites." (PMID 36145319, 2022). "CD4+ and CD8+ T cells with activity against IDO1+ and PD-L1+ cancer and immune cells were detected in the blood of the vaccinated patients." (PMID 36275666, 2022). "IDO1 expression in cancer tissues was detected, and then the function of IDO1 in the cells’ sensitivity to DDP was investigated in vitro and in vivo." (PMID 36233312, 2022). "Expression of IDO1 in cancer cells results in the suppression of an immune response, and therefore IDO1 inhibitors have been developed for use in anti-cancer immunotherapy." (PMID 35758198, 2022). "First, it is no surprise that KAT 1 (also known as CCBL1) is also significantly up-regulated in nine cancer types, 1 short of cancers expressing IDO1 and 3-4 short of those expressing FAMID and TDO2." (PMID 36286592, 2022). "Our research has resulted in a series of novel IDO1 inhibitors, which is beneficial to the development of drugs targeting IDO1 in numerous cancer diseases." (PMID 36355488, 2022).
cancer (continued). "Apart from those, various peptide vaccines targeting IDO1 have been tested in clinical research to assess their efficacy in cancer therapy." (PMID 35571116, 2022). "Considering the significance of IDO1 in cell proliferation and cancer-cell growth, Giglio and coauthors prepared [18F]3a and [18F]3b using a similar CMRF reaction to monitor IDO1 activity in vivo." (PMID 36297641, 2022). "IDO1 is up-regulated in a range of cancers, in particular, cervical cancer, diffuse large B-cell lymphoma, endometrial, head and neck squamous cell, lung and ovarian carcinomas." (PMID 36286592, 2022). "The expression of IDO1 affected the prognosis of patients in cancers by regulating the kynurenine pathway, inhibiting the proliferation of T cells." (PMID 36212460, 2022). "Focusing on cancer metabolism, we previously observed the impact of IDO1 on the efficacy of gDE7 immunization, with the complete rejection of TC-1 tumors in IDO1-deficient mice." (PMID 36405719, 2022). "This can help determine the path forward in the clinical development of IDO1 inhibitors for cancer therapy." (PMID 36119020, 2022). "Indoleamine 2,3-dioxygenase 1 (IDO1) is an attractive heme enzyme for its significant function in cancer immunotherapy." (PMID 35563059, 2022). "Immunotherapy targeting IDO1 has potential in cancer treatment, with some IDO1 inhibitors have gone beyond phase 2 clinical trials." (PMID 35997090, 2022). "While IDO1 has been shown to be primarily involved in immune regulation of cancer, TDO has been largely ignored." (PMID 35847038, 2022). "Especially, high expression of LAG3, CTLA4, PDCD1 (PD-1), IDO1, and CD274 (PD-L1) were widely reported to be associated with suppressive immune response and suppressed T cell function in cancer." (PMID 35902970, 2022). "At the same time, the concomitant tryptophan metabolites by IDO1 such as kynurenine in cancer cells further induce T-lymphocytes to undergo apoptosis, as well as promote activation of immunosuppressive regulatory T-cells." (PMID 36613455, 2022). "Due to this role in immune-oncology, small molecule inhibitors of IDO1 present a promising concept in cancer therapies." (PMID 35454819, 2022). "The emerging evidence of IDO1 inhibitors in cancer immunotherapy provides ideas for the transformation of erlotinib." (PMID 36034879, 2022). "Functionally, IDO1 has played a pivotal role in cancer immune escape by catalyzing the initial step of the Kyn pathway." (PMID 36119020, 2022). "In cancer immunity, IDO1 and TDO, which are highly expressed in various tumors, including colon and gastric cancers, are thought to be involved in the pathogenesis of immune tolerance in cancer cells." (PMID 35463998, 2022). "We found that IDO1 was necessary and sufficient for production of kynurenine, a downstream tryptophan metabolite, in cancer cells." (PMID 35150740, 2022). "A key question in clinical cancer therapy concerns the thus far reported poor or negligible efficacy of IDO1 inhibitors (IDO1i)." (PMID 35245456, 2022). "Generally, USP14 is a promising drug target for cancer therapy, especially in patients with high IDO1 expression." (PMID 36163134, 2022). "We recently identified Ido1-expressing Paneth-like cancer cells in tumors of ApcMin mice that prevent T cell infiltration and promote immune evasion." (PMID 36185806, 2022). "To date, numerous small molecule-selective IDO1 inhibitors have been studied in clinical trials to treat advanced cancers, such as epacadostat, BMS-986205, PF-06840003, indoximaod, NLG802, and LY3381916." (PMID 35571116, 2022). "Indoleamine 2,3-Dioxygenase 1 (IDO1) is a tryptophan catabolic enzyme that modifies inflammation and promotes cancer." (PMID 35739510, 2022).
cancer (continued). "In fact, several highly effective and selective IDO1 inhibitors have entered the clinical development stage for the treatment of human cancer." (PMID 35680848, 2022). "Treg cells are also involved in the role of IDO1-induced immunosuppressive mechanisms that promotes cancer cell survival." (PMID 36405719, 2022). "Overexpressed IDO1 in cancer cells makes cancer cells catabolize tryptophan leading to depletion of tryptophan." (PMID 36613455, 2022). "Several previous studies have reported that the administration of IDO1 inhibitors improves cancer treatment." (PMID 36545214, 2022). "IDO1 was originally thought to be an anti-cancer molecule because of its ability to deplete the tryptophan needed for cell metabolism and growth." (PMID 36386899, 2022). "As a result, compounds which chelate iron can be efficient inhibitors of IDO1 activity and IDO1 inhibitors have been developed for their iron complexation properties and their resulting anti-cancer activity." (PMID 36389710, 2022). "In a mouse model of the spontaneous gastrointestinal stromal tumor (GISTs), IDO1 regulation was shown to contribute significantly to imatinib's anti-cancer effects." (PMID 35918736, 2022). "Indoleamine 2,3-dioxygenase 1 (IDO1) plays a predominant role in cancer immunotherapy which catalyzes the initial and rate limiting steps of the kynurenine pathway as a key enzyme." (PMID 35677437, 2022). "The size-reduced, change-switchable, and acidity-triggered NPs were designed to improve cancer therapy by blocking the indoleamine 2,3-dioxygenase 1 (IDO1) pathway." (PMID 36134916, 2022). "Drug screening and functional assays revealed that HSP90 controls protein stability of the nuclear transcription factor STAT1 in a variety of different cancer cells, thereby promoting subsequent gene expression of immune checkpoint molecules (IDO1 and PD-L1)." (PMID 36158677, 2022). "Taken in context with the notion that anti-ferroptosis is a component of cancer cell survival, we noted that scant information is available about IDO1 expression in individual patient’s tumors." (PMID 35245456, 2022). "The dual inhibition sustained an increased production of IFNγ, TNFα, IL-12 and IL-6 by PBMCs, that contribute to expression of Ido-1 on cancer cells." (PMID 36419183, 2022). "According to our findings, KIF15 was highly related to IDO1 expression in 11 out of 33 cancer types." (PMID 35359374, 2022). "These are being investigated in the phase I/II CA224-048 study in which relatlimab will be administered in combination with nivolumab and either ipilimumab or an indolamine-2,3-dioxygenase (IDO)-1 inhibitor in patients with advanced malignant tumors." (PMID 35538491, 2022). "Studies have revealed that cancer cells specifically up-regulate IDO1 with the purpose of utilizing Trp metabolites as signaling molecules and also as a source of one-carbon donor for purine nucleotide synthesis for their proliferation." (PMID 35997090, 2022). "IDO1 expression is augmented in diverse types of cancers and often correlates with poor patient prognosis." (PMID 35159363, 2022). "It is worth noting that the proteolysis targeting chimera (PROTAC) technique has been used to degrade IDO1 as a strategy for cancer immunotherapy." (PMID 35571116, 2022). "For this reason, IDO1 catalytic inhibitors have been used as experimental drugs in cancer immunotherapy." (PMID 36319978, 2022). "IDO1 inhibitors have been in active clinical investigation and preliminary results suggest that IDO1 inhibitors produce additive efficacy when combined with cancer immunotherapies despite low activity as a single agent." (PMID 36304470, 2022). "Wnt5 also controls IDO1 activity in DC via β-catenin signaling while maintaining continuous expression in several cancer cell lines via an AhR-IL-6-STAT3 (Signal Transducer And Activator Of Transcription 3) signaling loop, according to new research." (PMID 35918736, 2022).
cancer (continued). "We also assessed the correlation between BMI1 expression and immune checkpoint-related molecules, including PD-L1, Galectin 9, HVEM, and IDO1, all of which are important marker genes for cancer immune therapy." (PMID 36199791, 2022). "For example, the expression status of PD-1/PD-L1, TGF-β1, and IDO1 was different among individuals even with the same type of cancer." (PMID 35799264, 2022). "Only 6 cancers were associated with expression of IDO2, 5 of which were associated with expression of the 2 Trp transporters, IDO1 and TDO2, and 2 with FAMID." (PMID 36286592, 2022). "A phase I study investigated the safety of navoximod (an IDO1 inhibitor) plus atezolizumab in 158 patients with advanced cancer." (PMID 35742834, 2022). "IDO1 is overexpressed in most cancers, and kynurenine levels in the TME correlate with poor prognosis in cancers such as melanoma, colon cancer, ovarian cancer, and AML." (PMID 35039633, 2022). "The overexpression and overactivation of the immunosuppressive enzyme indoleamine 2,3-dioxygenase 1 (IDO1) is a key mechanism of immune escape from cancer." (PMID 36588686, 2022). "Cancer cells unusually upregulate the expression of indoleamine 2,3-dioxygenase 1 (IDO1) that catalyzes the oxidation of L-tryptophan to N-formyl-kynurenine." (PMID 36613455, 2022). "IDO1 is expressed in about 58% of human tumors and is related to the adverse clinical outcomes of various cancers, including melanoma, gynecological cancer and hematological malignancies." (PMID 35494045, 2022). "Indoleamine 2,3-dioxygenase 1 (IDO1) has received much attention as an immunomodulatory enzyme in the field of cancer immunotherapy." (PMID 36355488, 2022). "In cancer, indoleamine 2,3-dioxygenase 1 (IDO1) and tryptophan 2,3-dioxygenase (TDO) catalyze the first and the rate-limiting step of tryptophan metabolism." (PMID 36185621, 2022). "Our research explored the possible association between IL-6 and IDO1 in the progress of HPV-related tumors, as well as their influence on a specific cancer immunotherapy strategy." (PMID 36405719, 2022). "In vivo, the serum kynurenine/tryptophan ratio has been directly associated with either IDO1 or TDO2 expression and is correlated with disease progression in multiple cancer types, including breast, lung, colon and liver carcinomas." (PMID 35681770, 2022). "Numerous studies have shown that IDO1 is significantly overexpressed in a variety of human cancers and mediates immunosuppression." (PMID 35886066, 2022). "According to cancer stages, IDO1 mRNA expression was positively correlated with plasma Kyn/Trp ratio in patients with earlier stages (I–II–III) but negatively correlated in patients with the late‐stage cancer (IV)." (PMID 36039641, 2022). "The gene expression data obtained from the TCGA database and immunolabeled samples show that the carcinomas of the cervix, followed by the endometrium, bladder, kidney, and lung, are the highest IDO1-expressing carcinomas." (PMID 36119020, 2022). "We previously reported that an IDO1 inhibitor enhances migration of PBMNCs towards carcinoma cells using HSC-3 cell line and two patients derived cancer cells." (PMID 35359980, 2022). "In this way, AHR is involved in cancer cell-mediated immunosuppression, PD-1 up-regulation in CD8+ T cells, and resistance to immune checkpoint inhibitors in different IDO-1 overexpressing cancer types." (PMID 34559251, 2021). "Increase in IDO1 expression with concurrent decrease in Trp leads to dysfunctional Teffs, permitting cancer immune evasion." (PMID 34122412, 2021). "It confirms that our method is selective for the determination of ʟ-Kyn production by IDO1 enzyme in cancer cells." (PMID 33541164, 2021). "The results clearly indicate the importance of using freshly collected cells to achieve a proper estimation of IDO1 activity in cancer cells." (PMID 33541164, 2021).
cancer (continued). "Over the last few decades, a multitude of compounds have been developed as IDO1 selective inhibitors for cancer immunotherapy and have been used in combinatorial therapies." (PMID 34685679, 2021). "IDO1 being an immunosuppressive enzyme is expressed in various tissues and cells under both normal and pathological conditions, including cancer cells." (PMID 33541164, 2021). "Based on these data, the inhibition of IDO1 has become an exciting approach as cancer immunotherapy and IDO1 inhibitors have been intensively investigated during the recent years." (PMID 33557876, 2021). "Given the biological importance of IDO1 in cancer immunotherapy, IDO1 has become an attractive target." (PMID 33883013, 2021). "As cancers can express both IDO1 and TDO, the industry has been pursuing the development of dual IDO1/TDO inhibitors." (PMID 33708223, 2021). "The opportunity of using IDO1 as a new prognostic marker or a molecular target in cancer treatment is recently considered in therapeutic approaches." (PMID 33541164, 2021). "In recent years, IDO1 inhibitors have been used as a promising immunomodulatory agent for patients with advanced cancer." (PMID 34778035, 2021). "The inhibition of IDO1 catalytic activity is currently under investigation in several clinical trials and at least eight small molecule IDO1 inhibitors are evaluated as possible new anti-cancer drugs." (PMID 33922388, 2021). "The model cells provide universal conditions for IDO1 activity assay considered in cancer cell research." (PMID 33541164, 2021). "Interrogation of the TGCA and METABRIC databases confirmed that high expression of IDO1 and LAG3 was associated with poor survival in luminal B cancers." (PMID 34359625, 2021). "While serine is considered the primary source of one-carbon units in cancer cells, the present study highlights that in IDO1-expressing cancer cells, tryptophan is potentially a major alternative source of one-carbons for the THF cycle." (PMID 33831358, 2021). "Several reviews discussing the biochemical properties and physiological functions of IDO1 and the therapeutic applications of IDO1 inhibition in cancer and other diseases have been published." (PMID 33557876, 2021). "These comparisons demonstrate that the KPC-IDO1 cells stably express levels of IDO1 comparable to immune-driven IDO1 expression in human cancer cells." (PMID 33831358, 2021). "We show that when IDO1 is expressed by cancer cells, it promotes the generation of one-carbon units from tryptophan that are used in de novo purine nucleotide synthesis." (PMID 33831358, 2021). "To clarify, among the EBV-associated cancers that were studied, only EBV(+) GC was associated with both IDO2 and IDO1." (PMID 34944437, 2021). "The imbalances in the level of TRP and KYN as well as the overexpression of IDO1 have been reported in many cancers." (PMID 33557876, 2021). "As excepted based on previous HPLC-DAD measurements, IDO1 activity estimated by UHPLC-MS/MS (run in triplicates) in SK-OV-3 cancer cells were much higher compared to MDA-MB-231 cells." (PMID 33541164, 2021). "Visualization of drug engagement and its correlation with immunoediting efficacy would provide direct evidence for improving the therapeutic outcomes of patients with cancer receiving IDO1-blockade in a therapeutic setting." (PMID 34148865, 2021). "IDO1 is overexpressed in various cancer types and is involved in suppression of effector T and NK cell function and in promotion of angiogenesis in solid tumors." (PMID 34439305, 2021). "More than 20 ongoing clinical trials are investigating the ability of IDO-1 to enhance the therapeutic effect of standard anti-cancer therapies." (PMID 34685679, 2021). "This in total points to IDO1 being a promoter of epithelial-to-mesenchymal transition and a factor that facilitates a gain in motility capacity by cancer cells." (PMID 34071442, 2021).